GSDMB (gasdermin B)
Diseases named in the same sentence as GSDMB in open-access papers (continued):
Sharing a sentence is not in itself a finding about the gene and the disease.
asthma (continued). "In summary, this study has provided a greater insight into the relative contribution of asthma GWAS SNPs to clinically relevant endpoints in asthmatic children and further defines the diverse role of GSDMB SNPs particularly in lung function and disease severity." (PMID 24066901, 2013). "The asthma-associated region 17q12-q21 harbors three genes, the zona pellucida binding protein 2 (ZPBP2), gasdermin B (GSDMB) and ORM1-like 3 (ORMDL3), that show allele-specific differences in expression levels in lymphoblastoid cell lines (LCLs) and CD4+ T cells." (PMID 22271045, 2012). "To validate whether ORMDL3 is a risk factor for adult-onset asthma, we sought to replicate the association of polymorphisms in ORMDL3, GSDMB, ZPBP2 and IKZF3 and asthma in an adult Chinese Han population." (PMID 21985515, 2011). "Review of previous T1D genome-wide association results revealed that four (human leucocyte antigen (HLA), gasdermin B/ORM1 (Saccharomyces cerevisiae)-like/gasdermin B/, GSDMB/ORMDL3/GSDMA and IL2RB) of ten loci recently reported to be associated with asthma were associated with T1D (p≤0.005)." (PMID 22069270, 2011). "Thus, the inhibition of NLRP3- or GSDMB-mediated pyroptosis in AECs may reduce asthma severity and exacerbations." (PMID 39611173, 2024). "A study identified that only GSDMB and maybe GSDMA members of the GSDM family are linked to asthma." (PMID 40104184, 2024). "However, whether and how full length GSDMB promotes airway inflammation in patients with asthma remains unclear." (PMID 38737375, 2024). "We found that CISDs associate with the 17q21 locus (GSDMB/ZPBP2) as well as TSLP, IL33, and the gene encoding the IL33 receptor, IL1RL, which all have previously shown to be associated with asthma, and have also shown to be functionally relevant in asthma models." (PMID 36653354, 2023). "While the presence of the GSDMB polymorphism alone might not be sufficient to associate with the high risk of developing asthma or responding to it in adults in Jordanian population." (PMID 36201519, 2022). "Additionally, GSDMB is an executioner of pyroptosis and is related to the pathogenesis of asthma." (PMID 35819638, 2022). "Furthermore, the mechanism that allows GSDMB SNP to be high-risk factor for developing asthma exclusively in childhood but not adulthood should be further investigated." (PMID 36201519, 2022). "Strikingly, the asthmatic phenotype of the hGSDMBZp3−Cre model was mechanistically mediated by the transcriptional regulation of certain genes, not via a cell death mechanism, while in human lung cells asthma has been linked to the pyroptotic effect of specific GSDMB isoforms." (PMID 35281099, 2022). "GSDMB SNP may increase susceptibility to asthma development in childhood, but in a way independent of IgE release." (PMID 36201519, 2022). "However, additional studies are required to determine whether GSDMB can be cleaved by inflammatory caspases in asthma." (PMID 34858408, 2021). "Furthermore, it might be that unknown environmental influences affect the relationship of ORMDL3/GSDMB with asthma, which may explain the difference between our findings and those of others." (PMID 25768087, 2015). "In summary, we report significant associations of asthma with rare or low-frequency variants in two novel genes, GRASP and MTHFR, in Latinos and the African ancestry sample, respectively, and with a potentially damaging common missense mutation in GSDMB in Latinos and the combined sample." (PMID 25591454, 2015). "It is important to note, however, that while the current experimental evidence excludes IKZF3 (IKZF3 is not affected by the haplotype effect in LCLs or T lymphocytes), it is not sufficient for ruling out ZPBP2, GSDMB or GSDMA as contributors to predisposition to asthma." (PMID 22271045, 2012).
asthma (continued). "Eligible studies included pediatric populations with asthma or wheeze phenotypes assessing predefined genetic (ORMDL3, GSDMB) or epigenetic (AHRR, FOXP3, CpG loci) markers and reporting odds ratios (ORs) or sufficient data for their derivation." (PMID 41682911, 2026). "A genome‐wide study of early and severe childhood asthma pointed to a significant interaction between another known gene for asthma, CDHR3, and GSDMB." (PMID 40133993, 2025). "Located in the intronic region of the GSDMB gene, this SNP regulates the expression of ORMDL3, playing a significant role in childhood asthma development." (PMID 40452932, 2025). "Moreover, a whole-genome sequencing association study of asthma severity in Europeans evidenced eight genome-wide significant loci previously reported as associated with asthma (IL1RL2, TSLP, HLA-DQA1, BACH2, C11orf30, RAD51B, and GSDMB) and lung function (THSD4)." (PMID 37761964, 2023). "Mice engineered to express human GSDMB develop an asthma phenotype, while in IBD increased GSDMB expression in colonocytes was reported to promote intestinal epithelial repair independent of its pyroptotic signaling capacity." (PMID 35608339, 2022). "GSDMA, GSDMB, and ORMDL3 are statistically independent genetic effects from all shared TWAS genes between asthma and HF." (PMID 35126453, 2021). "We identified three genes (GSDMA in chr17, GSDMB in chr17, and ORMDL3 in chr17) with statistically independent genetic effects from all of the shared TWAS genes between asthma and HF." (PMID 35126453, 2021). "For example, we showed that one of the candidate genes in the core region, ORMDL3, is downregulated by RV in cultured AECs, and that an eQTL for ORMDL3 colocalizes with a meQTL in a neighboring gene, GSDMB, and with a TAGC asthma GWAS SNP." (PMID 34629083, 2021). "However, the mechanism whereby GSDMA and GSDMB promote the onset of asthma is largely unknown." (PMID 34590363, 2021). "The locus 17q21 is the most replicated in asthma GWASs, including many other important asthma genes such as ORDLM3 and GSDMB." (PMID 33133517, 2020). "This previous study identified genes on chromosomes 2 (IL1RL1/IL18R1), 6 (HLA-DQ), 9 (IL33), 15 (SMAD3), 17 (ORMDL3/GSDMB), and 22 (IL2RB) correlated with asthma." (PMID 32512817, 2020). "Associations were found in the current childhood asthma GWAS with known asthma loci in IL1RL1, IL13, LINC01149, near GSDMB, and in the C11orf30-LRRC32 region (Bonferroni adjusted p < 0.05 for all comparisons)." (PMID 30373671, 2018). "One of the major findings was the identification of the ORMDL3 (ORM1-like protein 3) and the GSDMB (Gasdermin-B) genes within 17q21 locus and CDK12 (Cyclin-dependent kinase 12) as candidate genes for childhood-onset severe asthma." (PMID 29992143, 2018). "Some genes detected by GWAS have shown the potential as asthma biomarkers in a specific age group, e.g. ORMDL3/GSDMB in children." (PMID 27658857, 2016). "Furthermore, higher GSDMB expression correlates with an increased number of exacerbations and with genes related to interferon signaling and the TH1 pathway in adult asthma." (PMID 40687950, 2025). "Interestingly, previous studies suggest potential roles for GSDMB and ORMDL3 expression in asthma pathobiology." (PMID 39299705, 2024). "A functional splice variant rs11078928 lost 13 critical amino acids in the N‐terminal domain of GSDMB, thus inhibiting asthma by blocking pyroptosis." (PMID 37125240, 2023). "The pathogenesis of PV and GSDMB has not been reported, but genes in this region have been associated with immune-mediated inflammatory diseases (IMID) such as asthma." (PMID 36607980, 2023). "Furthermore, the expression of canonical PRGs, such as GSDMB, caspase-4, and NLRP1, was upregulated in the poorly controlled asthma subtype." (PMID 35967302, 2022). "Protein kinases, adapter protein, miRs, ORMDL3, and gasdermin B are newly identified molecules that contribute to asthma pathogenesis, independent of inflammation." (PMID 36078171, 2022).
asthma (continued). "In fact, using GEMM models, only the mechanistic implication of GSDMB3 has been demonstrated in asthma, while the GSDMB bactericidal function was not validated in GSDMB1 KI mice." (PMID 35281099, 2022). "Protein kinases, adapter protein, microRNAs, ORMDL3, and gasdermin B are newly identified molecules that drive asthma progression, independent of inflammation." (PMID 36078171, 2022). "Previous studies reported that GSDMB and ORMDL3 are associated with asthma, but their association with HF was not reported." (PMID 35126453, 2021). "GSDMB and ORMDL3 were also confirmed to be shared between asthma and HF using TWAS in our study." (PMID 35126453, 2021). "In addition to THSD4 and HIVEP2, age-by-genotype interactions also prioritized genes previously identified as asthma candidate genes, including DPP10, HDAC9, TBXAS1, FBXL7, and GSDMB/ORMDL3, as pharmacogenomic loci as well." (PMID 32119686, 2020). "The first GWAS for asthma was completed involving 994 childhood-onset asthma patients and 1,243 non-asthma controls and identified single nucleotide polymorphisms (SNPs) within chromosome 17q21 spanning the ORMDL3/GSDMB genes." (PMID 24066901, 2013). "The first GWAS for childhood asthma identified ORMDL3 (and GSDMB) also present in the 17q21 region." (PMID 22188591, 2011). "According to reports, GSDMB may control the release of TSLP, IL-33, and IL-25, which are critical for the pathophysiology of asthma, by encouraging the infiltration of neutrophils and eosinophils in the inflamed airways; this is more pronounced in individuals with the T/C or T/T genotype." (PMID 39906448, 2025). "Therefore, GSDMB, PGAP3, and ORMDL3 are the leading candidate asthma genes." (PMID 37064151, 2023). "Furthermore, GSDMB transgenic mice assume asthma symptoms in the absence of airway inflammation, implicating that the induction of GSDMB triggers asthma." (PMID 30891811, 2019). "Indeed, nuclear GSDMB provokes the transcriptional induction of the same set of genes (TGF-β1 and 5-lipoxygenase) in human bronchial epithelial cells and the lungs of the hGSDMBZp3−Cre KI model (ubiquitously expressing the longest isoform, GSDMB3) after asthma challenge." (PMID 35281099, 2022). "The flow central nodes occurring within the network paths connecting GSDMB to the COPD seed genes show strong differential expression patterns, hinting that these genes could participate in the molecular mechanisms carrying the perturbation from the asthma-specific to the COPD-specific domain." (PMID 32041952, 2020). "Although the exact role of pyroptosis activation in the experimental animal models of asthma is not completely clear, the key complexes such as NLRP3, GSDMB, GSDME, etc., and related signaling pyroptosis pathways are still promising therapeutic strategies." (PMID 36248872, 2022). "Taken together, these findings suggest that type 2 inflammation may not be essential for the relationship between rs7216389 in GSDMB/ORMDL3 and asthma exacerbations." (PMID 40687950, 2025). "Moreover, expression of RANTES was more significantly correlated with GSDMB in asthmatic nasal epithelial cells compared to control subjects in the Genes-environments and Admixture in Latino Americans (GALA) II study (n = 254 controls and 441 with asthma)." (PMID 38737375, 2024).
breast carcinoma (58 papers, 2014 to 2025). "In HER-2–positive breast cancer, about 65% cases show GSDMB gene overexpression, which is linked to poor clinical outcomes, including poor therapeutic response and lower survival." (PMID 38711020, 2024). "In contrast to its role in IBD and CRC, heightened GSDMB levels are intricately linked to the aggressive characteristics of breast cancer, specifically its invasive nature, progression, and metastatic potential." (PMID 38304430, 2024). "They found that overexpression of GSDMB in breast cancer cells is associated with increased cell motility and invasiveness so exhibits prometastatic influence." (PMID 38693919, 2024). "For instance, studies have reported the upregulation of GSDMB in breast cancer, and its expression has been associated with the progression and poor prognosis of breast cancer." (PMID 38066523, 2023). "Specifically, overexpression of GSDMB in breast cancer has been found to be associated with tumor progression, which indicated unfavorable response to targeted treatment of HER-2." (PMID 37950289, 2023). "Marta Hergueta-Redondo uncovered the initial functional significance of GSDMB in breast cancer and the overexpression of GSDMB are closely linked to increased metastasis and reduced survival in breast cancer patients." (PMID 36119049, 2022). "It has been found that treatment failure of aggressive HER2 positive breast cancers is associated with the coamplification and coexpression of an Erb2 neighbour gene, namely, the GSDMB gene." (PMID 35626754, 2022). "Our previous work proved that GSDMB over-expression is a maker of poor prognosis associated with trastuzumab resistance in HER2 breast carcinoma patients in both neoadjuvant and adjuvant treatment settings." (PMID 36163066, 2022). "While GSDMB over-expression in human breast cancers, specially the HER2 subtype, associates with disease aggressiveness, we only detected one case of spontaneous breast carcinoma in the GB2+/+ mice." (PMID 35281099, 2022). "In breast cancer, the cell survival rate is strongly linked to the expression of the Gasdermin B gene (GSDMB)." (PMID 34369076, 2021). "GSDMB expression was elevated in HER2-postive breast cancer and high GSDMB expression associated with poor prognosis." (PMID 34830775, 2021). "The results of the gene expression analyses indicate that GSDMB over-expression associates with poor prognosis of HER2-positive breast cancer." (PMID 27462779, 2016). "Second, to demonstrate the association of GSDMB with resistance in vivo we utilized six breast cancer Patient Derived Xenografts (PDX), a more clinically relevant model." (PMID 27462779, 2016). "Our in silico analyses indicates that GSDMB over-expression is associated with the HER2-positive phenotype in breast cancer." (PMID 27462779, 2016). "In summary, we have shown that GSDMB up-regulation in breast cancer associates to poor prognosis and increased metastasis." (PMID 24675552, 2014). "In the case of human epidermal growth factor receptor 2 positive (HER2+) breast cancer, Gasdermin B (GSDMB) overexpression was found to be associated with increased resistance to therapy and aggressive tumor behavior, indicating its role in protective autophagy." (PMID 38398197, 2024). "GSDMB has also been linked with invasion and metastasis in breast cancer cells and in CC." (PMID 36929174, 2023). "Importantly our data also revealed that the expression of GSDMB pyroptotic-proficient and -deficient isoforms differentially correlate with clinic-pathological parameters in breast carcinomas." (PMID 36899106, 2023). "Although expression levels of GSDME and GSDMB were positively correlated with clinical benefit in several kinds of cancers, increased GSDMB expression was associated with poor clinical outcome in breast cancer." (PMID 33406603, 2021).
breast carcinoma (continued). "In patients with human epidermal growth factor receptor 2-positive breast cancer, increased GSDMB in tumor cells is associated with an increased incidence of metastasis, reduced survival, poor response to human epidermal growth factor receptor 2-targeted therapy, and poor prognosis." (PMID 34858408, 2021). "Importantly, GSDMB expression promotes survival to trastuzumab in different HER2-positive breast carcinoma cells, and is associated with trastuzumab resistance phenotype in vivo in Patient Derived Xenografts." (PMID 27462779, 2016). "Importantly, we corroborated that GSDMB expression is associated with trastuzumab resistance phenotype in HER2-positive breast carcinoma cells and in Patient Derived Xenografts." (PMID 27462779, 2016). "Interestingly, high levels of GSDMB are correlated with a poorer response to HER-2 targeted therapy in breast cancer, and may be associated with the malignant phenotype of gastric cancer." (PMID 35990696, 2022). "The delivery of anti‐GSDMB antibodies using nanocapsules in the treatment of breast cancer enhances the binding of GSDMB to sulfatides." (PMID 40783818, 2025). "Targeting GSDMB with antibodies has been shown to reduce its pro-tumor functions (e.g., cell migration, metastasis, and drug resistance) in breast cancer cells." (PMID 40452932, 2025). "GSDMB‐1 also localizes to the nucleus of the human breast cancer cell line MCF7 and the human cervical cancer cell line HeLa, whereas it is exclusively found in the cytoplasm of the hepatocellular carcinoma cell line HepG2." (PMID 40783818, 2025). "GSDMB expression is correlated with a shorter survival time and increased metastasis in breast cancer." (PMID 38711020, 2024). "Decreased GSDME is related to lymph node metastasis and worse prognosis in breast cancer, but GSDMB can be a tumor promoter that induces invasion and metastasis in breast cancer cells." (PMID 38221934, 2024). "For example, for fusion TATDN1::GSDMB in breast cancer cell line SKBR3, we find evidence of 13 distinct fusion transcript isoforms." (PMID 38464114, 2024). "In human epidermal growth factor receptor 2-positive breast cancer, GSDMB promotes metastasis, and indicates a poor prognosis and weaker therapeutic response." (PMID 38711020, 2024). "This positions GSDMB as a promising candidate for breast cancer detection and prognostic assessment." (PMID 38304430, 2024). "Elevated levels of GSDMB often correlate with invasive tendencies in various cancers, including GC, breast cancer, cervical cancer, and CRC." (PMID 38304430, 2024). "Anti-GSDMB antibody treatment can inhibit the growth, migration, and metastasis of breast cancer cells and enhance their sensitivity to trastuzumab." (PMID 38711020, 2024). "To assess this possibility, we first validated our results using two cancer cell models, 23132/87 (gastric cancer cell line) and SKBR3 (HER2 breast cancer) with very low or undetectable expression of GSDMB." (PMID 36899106, 2023). "GSDMB is widely expressed in both normal tissues and various tumor cells, including gastric cancer, cervical cancer, breast cancer, and hepatocarcinoma." (PMID 38066523, 2023). "In patients with human epidermal growth factor receptor 2 positive (HER2+) breast cancer, high GSDMB expression levels correlate with poor prognosis and poor therapeutic response." (PMID 37627547, 2023). "Intriguingly, targeted anti-GSDMB nanotherapy effectively restricted HER2 breast cancer cell aggressiveness and specifically increased sensitivity to trastuzumab." (PMID 36823153, 2023). "When referred to different molecular types of breast cancer, GSDMB is found to be intensively amplified in HER2-positive breast cancer and is related to poor prognosis." (PMID 36823153, 2023). "GSDMB expression was linked to a poor prognosis and treatment response in HER2‐positive breast cancer." (PMID 37752941, 2023).